COL1A1 (collagen type I alpha 1 chain)
Diseases named in the same sentence as COL1A1 in open-access papers (continued):
Sharing a sentence is not in itself a finding about the gene and the disease.
tumor (continued). "Thereby, in PDAC, αSMA+COL1A1+ CAFs may constitute a tumor‐restricting myofibroblast population." (PMID 39563958, 2024). "Interestingly, we also identified several interactions between COL1A1+ CAFs and all epithelial cells, which could be specific for tumor cells and Scissor+ tumor cells, and be highly dependent on the SDC1 receptor." (PMID 37021816, 2023). "Collectively, COL1A1 down-regulation may inhibit exosome secretion possibly via inhibiting COL I and upregulating CAV-1, thereby inhibiting tumor-associated fibroblast activation and matrix remodeling in the tumor microenvironment." (PMID 38045487, 2023). "Additionally, p28 co-administration with iRGD and 5-FU, or therapy with p28 and 5-FU, dramatically decreased the expression of the CoL1a1 and CoL1a2 genes in the tumor tissues when compared with the mice receiving solo therapy with p28 or 5-FU (P<0.05 and P<0.001, respectively)." (PMID 37396945, 2023). "Therefore, there may be a regulatory relationship between the COL1A1 and tumor microenvironment matrix remodeling." (PMID 38045487, 2023). "In particular, genes encoding collagen, including COL1A1, COL1A2, COL6A1, and COL6A3, are upregulated in tumor tissue and also highly expressed in late-stage cancer patients; they are predicted to interact with SDC1 and SDC4 in tumor cells to promote the pEMT phenotype of tumors." (PMID 38002057, 2023). "In our study, the data from qRT-PCR, WB, and dual luciferase reporter assay solidly confirmed that miR-29b-3p directly targeted COL1A1 and COL5A1 3′‐UTR and thus caused degradation of type I and V collagens, which could explain the downregulation of miR-29b-3p in clinical tumor tissues." (PMID 35530352, 2022). "COL1A1 could promote the tumor progression in multiple types of cancer." (PMID 35789341, 2022). "Thus, our research suggests that COL1A1 may have a potential role in tumor immunology and provide a theoretical basis for being a biomarker of LGG." (PMID 35789341, 2022). "COL1A1 may also contribute to tumor progression by promoting EMT." (PMID 35669725, 2022). "Moreover, COL1A1 overexpression is also related to tumor aggressiveness and poor clinical outcomes." (PMID 30568862, 2018). "However, broadly the expression of Col1a1 in 4T1 tumours was equivalent to that found in the skin." (PMID 30054470, 2018). "Notably, celecoxib decreased α-SMA+ fibroblasts within the PyMT/Col1a1 tumor microenvironment." (PMID 27000374, 2016). "The COL1A1-PDGFB fusion gene was detected in both imatinib-resistant and imatinib-sensitive tumors and COL1A1-PDGFB rearrangement was reconfirmed by PCR, but no point mutation or copy number change was detected in the PDGFB gene of the imatinib-resistant tumor." (PMID 23922791, 2013). "In C1-GBM, key tumor driver genes included BIRC3 (Baculoviral IAP Repeat Containing 3), MET (MET Proto-Oncogene, Receptor Tyrosine Kinase), COL1A1 (Collagen Type I Alpha 1 Chain), CR1 (Complement C3b/C4b Receptor 1), and IL7R (Interleukin 7 Receptor)." (PMID 41614933, 2026). "For example, MAPK10 isoforms showed distinct phenotypic correlations, while COL1A1 and UMOD displayed gene-level coordination in regulating tumor stemness." (PMID 41048343, 2025). "COL1A1 and EMP1 were significantly upregulated in tumor tissues, while MYH11 and SASH1 were significantly downregulated." (PMID 41099090, 2025). "Secondly, COL1A1 was also highly expressed in TN2, TN3, and TME3 and in the depth of the tumor of ID08 and ID15." (PMID 40076457, 2025). "The significant up-regulation of COL1A2, COL1A1 and DCN in the TME of CC illustrates the phenomenon of fibroblasts’ activation in the tumor microenvironment." (PMID 40124621, 2025). "This study investigates the upregulation of COL1A1 in KIRC and explores the impact of COL1A1 on tumor cell proliferation, migration, invasion, and EMT." (PMID 40851082, 2025).
tumor (continued). "Genes Ptgs2, Cxcl1, Vegfa, Cxcl2, Col1a1 and Col1a2 were downregulated in cluster 0 of the A101 CAR-T-treated tumor compared to the mock-T-treated group which are involved in angiogenesis and tumor-promoting inflammation as well as EMT and tumor progression." (PMID 40568084, 2025). "While the enrichment of ECM-related pathways is in line with the known roles of THBS2, FN1, COL1A1, and COL5A1 in extracellular matrix remodelling and tumour progression, the concurrent upregulation of mTOR signalling presents an intriguing finding." (PMID 40860666, 2025). "The final classification consisted of (i) tumor areas (FOXL2+/COL1A1−, considered pure tumor) and (ii) collagen-rich areas, including FOXL2−/COL1A1+ stroma, FOXL2+/COL1A1+ stroma, and FOXL2+/COL1A1+ fibromatous tumor." (PMID 41042551, 2025). "The identification of gene co-expression modules containing classical EMT markers (e.g., VIM, ZEB1, SNAI2) alongside ECM-related genes (COL1A1, FN1, SPARC, LOX) underscores a tightly coordinated interaction driving tumor cell plasticity and invasion." (PMID 40943497, 2025). "Specifically, MYOC, TBK1, COL1A1, and COL1A2 were upregulated in tumor tissues, while FOXC1, LRP2, and TEK was downregulated (all p < 0.05)." (PMID 40808675, 2025). "Silencing COL1A1 effectively inhibited KIRC cell proliferation, migration, and invasion, highlighting its important regulatory role in tumor progression." (PMID 40851082, 2025). "Within the study, the authors found that COL1A1 and MMP9 were also amongst the most upregulated genes in tumor cells that were co‐cultured with CAFs." (PMID 39245631, 2025). "Based on this expanded analysis of IMC marker co-expression, FOXL2+COL1A1+ cells can be separated into two subgroups, one resembling FOXL2+COL1A1− tumor cells and the other with an immunophenotype resembling non-AGCT stromal cells." (PMID 41042551, 2025). "All four candidate genes (THBS2, FN1, COL1A1, COL5A1) were found to be upregulated in tumour samples compared to matched normal samples in our microarray analysis." (PMID 40860666, 2025). "Canonical markers were used to annotate different cell types: malignant cells (COL1A1, IBSP), myeloid cells (CD74, CD14), osteoclasts (CTSK, MMP9), pericytes (RGS5, ACTA2), endothelial cells (PECAM1, VWF), and tumor-infiltrating lymphocytes (CD3D, NKG7)." (PMID 40730548, 2025). "First, COL1A1 staining was used to identify collagen-rich regions, followed by FOXL2 staining to define pure tumor areas." (PMID 41042551, 2025). "For example, in COL1A1, COL1A2, COL3A1 and COL5A1 HYP peptides were enriched in the tumor nodule boundaries, a pattern that was lost in P4HA2-depleted tumors." (PMID 40671813, 2025). "Initially, we aimed to define tumor and stromal regions based on FOXL2 and COL1A1 staining, respectively." (PMID 41042551, 2025). "Cancer-associated fibroblasts are important contributors to the EMT featured in the tumor microenvironment, and the EMT phenomenon and the level of COL1A1 and COL1A2 were closely correlated." (PMID 40124621, 2025). "This showed that universal (PI16+) fibroblasts from tumours show evidence of activation and inflammatory changes (including expression of FAP, COL1A1, IGF1)." (PMID 39757146, 2025). "CSR‐related genes (COL1A1, LOXL2, LUM, FN1, and TGFB1) reflect extracellular matrix deposition and stromal activation, hallmarks of invasive tumor behavior." (PMID 41407509, 2025). "Specifically, ALB and CYP2E1 were highly expressed in normal areas, GPC3 and AKR1B10 were highly expressed in tumor areas, ACTA2 and COL1A1 were highly expressed in fibrostic areas, and PTPRC was highly expressed in inflammation areas." (PMID 40051627, 2025). "Overexpression of collagen genes (COL1A1 and COL5A2) and dysregulation of ECM enzymes further highlight the stromal contribution to tumor aggression." (PMID 40507957, 2025).
tumor (continued). "Of note, those groups of FOXL2+COL1A1+ cells, besides positivity for COL1A1, had higher expression of αSMA, PDGFRa, and FAP (frame 2) than FOXL2+COL1A1− tumor cells themselves (frame 1)." (PMID 41042551, 2025). "Concurrently, mechanosensitive YAP/TAZ signaling in fibrotic liver tissues promotes COL1A1 secretion, establishing a self-reinforcing “COL1A1-tissue stiffness-YAP” tumor-promoting microenvironment." (PMID 41039598, 2025). "Most samples had more than 50% of pure tumor area, which was FOXL2+COL1A1− and exhibited a distinguishable border between COL1A1+ and FOXL2+ staining areas." (PMID 41042551, 2025). "Wnt/β-catenin signaling activates CTNNB1 (β-catenin) through WNT1, promoting the expression of collagen (such as COL1A1 and COL28A1), thereby increasing the adhesion and matrix invasion ability of tumor cells." (PMID 40989695, 2025). "After treatment with CM from tumor cells, LX2 cells transformed from spindle shaped to radial, with increased protrusions, upregulated activation marker (ACTA2, COL1A1, DES) expression, and downregulated quiescence marker (RGS5) expression." (PMID 41214328, 2025). "Based on our data, CD8 Tex cells in LN-out upregulate of TGF-β1, IFN-γ, and ITG-β1, which subsequently target FN1, EGFR, CTNNB1, and COL1A1 in tumor cells, activating the ERK1 and ERK2 cascade pathways and facilitating tumor progression." (PMID 38519500, 2024). "Specifically, the proportions of COL1A1+ macrophages and GZMA+ macrophages deceased in tumor groups, while CXCL3+ macrophages appeared exclusively in tumor samples." (PMID 39112478, 2024). "The previous study highlighted the importance of hydroxyproline content, indicating that the presence of hydroxyprolines on peptides from COL1A1 and COL1A2 determined their histopathologic location in inflammatory regions (less HYP) or tumor (more HYP)." (PMID 39347566, 2024). "In NPC, miR-29a-3p is known as a tumor suppressor and can improve radiotherapy sensitivity of NPC cells by targeting COL1A1." (PMID 38649975, 2024). "Immunofluorescence microscopy revealed that tumor cells induced CAF biomarkers, αSMA and COL1A1, in stromal fibroblasts." (PMID 38322789, 2024). "Checking the tissue distribution of each subset revealed multiple tumor-enriched subsets, including all tip cell subsets, E12-capillaries-FABP4, and E16-arteries-COL1A1." (PMID 39345334, 2024). "Key genes, including IL6, IL1B, and COL1A1, emerged from GSEA and tumor prediction analysis, highlighting the broad relevance of these genomic alterations across diseases." (PMID 39635438, 2024). "The findings revealed that COL1A1 expression correlated with CD248 expression in LUAD and LUSC tumour tissues relative to that in NAT tissues." (PMID 39164826, 2024). "In short term survival samples, 2 stroma clusters near the tumor edge expressed high COL1A1 and POSTN consistent with myofibroblast phenotype, while two stroma clusters distal to the tumor edge expressed high COL1A1 and CD36 (peri-vascular)." (PMID 38525245, 2024). "COL1A1 can enhance the activity of MMPs, particularly MMP2, which degrade the ECM and facilitate tumor cell invasion and metastasis." (PMID 39065771, 2024). "This translocation leads to the formation of a fusion protein known as COL1A1-PDGFB, which stimulates tumor growth by promoting the excessive production of platelet-derived growth factor (PDGF)." (PMID 38865945, 2024). "In turn, CD8 Tex cells in the LN-out highly expressed TGF-β1, IFN-γ, and ITGB1, which target FN1, EGFR, CTNNB1, COL1A1, and CFLAR in tumor cells, activating downstream pathways including ERK1 and ERK2 cascade." (PMID 38519500, 2024). "Its targets have been reported to be IL-8, COL1A1, ADAM9, HMGB1, and SLC2A3, and inducing mir-129-5p overexpression in tumor cells reduced malignant characteristics, including cell proliferation, migration, and invasion." (PMID 39797181, 2024).
tumor (continued). "The genetic deletion of the Col1a1 gene in CAFs expressing α-smooth muscle actin (α-SMA) results in the suppression of anti-tumor immunity and tumor progression in a PDAC mouse model." (PMID 38849479, 2024). "In particular, CTHRC1+GREM1+ myCAF expressed high levels of collagens, including type-1 (COL1A1, COL1A6), type-3 (COL3A1), type-5 (COL5A2), and type-6 (COL6A1), which contribute to tumor cell migration and proliferation through collagen/integrin interactions." (PMID 39075108, 2024). "In contrast, eight genes (COL1A1, COL5A1, COL1A2, COL3A1, WNT2, C1QTNF3, ADAMTS2, GXYLT2) exhibited elevated expression in tumor compared to normal tissue." (PMID 39062832, 2024). "Staining revealed MCAF localization in large patches encasing tumor cells and at the tumor-stroma border, while iCAFs were intermixed with MMP1-, COL1A1 cells clustered within tumors." (PMID 38525245, 2024). "In NED tumor tissues, which had far more variability in protein species detection, the top three most abundant species were also COL1A2, COL1A1, and COL3A1, respectively." (PMID 39347566, 2024). "A unique molecular signature intrinsic to oncostreams, with overexpression of key genes (i.e., COL1A1, ACTA2) that drive the tumor's mesenchymal transition and malignancy is also identified." (PMID 38384234, 2024). "And more COL1A1 and BGLAP are expressed in the tumor than normal prostate by analyzing the spatial transcriptomics data." (PMID 37564213, 2023). "The extracellular matrix (ECM) includes fibrillar collagens (e.g. COL1A1, COL5A2, COL11A1) as the major connective tissue components and tumor microenvironment." (PMID 36587397, 2023). "The TCGA and GETx datasets indicated that COL1A1, COL3A1, COL5A2, COL8A1, COL10A1, and COL12A1 genes were expressed much higher in tumor tissues than in the normal ones." (PMID 36900272, 2023). "CAFs in endometrial carcinoma, identified by classic fibroblast markers ATCA2, COL1A1, COL3A1, and THY1, are divided into four subsets with distinct characteristic and exclusive expression patterns that perform unique functions in the tumor ecosystem." (PMID 37046676, 2023). "Taken together, we suggest that COL1A1 in fibroblasts and CD44 epithelial/malignant cells interact interdependently, facilitating tumor progression." (PMID 36828832, 2023). "One lineage, the TGFβ-responsive myofibroblast CAF population, is located in the tumor nests, originates from stellate cells, and generates ECM mRNAs and TGFβ-induced genes such as Col1A1, Col5A1, Ctgf, smooth muscle α-2 actin (Acta2), or vimentin (Vim)." (PMID 37046676, 2023). "We focused on two regulators, COL1A1 and BGLAP, and observed their significantly positive correlation with most tumor-infiltrating immune cells." (PMID 37564213, 2023). "Along with Col1A1, a significant decrease of FN1 in viable tumor regions was detected with VEGF overexpression." (PMID 37389973, 2023). "After COL1A1 knockout, Western blot was employed to examine the expression of fibrosis-related proteins (E-cadherin, α-SMA, FAP, and Cav-1) in the tumor microenvironment, aiming to determine any alterations in matrix fibrosis levels." (PMID 38045487, 2023). "The effectiveness of using a combinational therapy including SeNPs, MSCs, and LDR was elucidated by measuring the expression of some genes including Serpin, MIF, LOX-1, COL1A1, FST, and ADRP that play a role in the tumor microenvironment." (PMID 35138531, 2023). "We further identified the top 100 specifically expressed genes in the tumor boundary of the three CRC ST samples which overlapped significantly, and included SPP1, MMP11, and COL1A1." (PMID 36806082, 2023). "Cluster 8 ECs (COL1A1, COL1A2, COL3A1, PDGFRB, and ACTA2) showed an endothelium-mesenchymal transformation phenotype, contributing to tumor progression and metastasis." (PMID 37533434, 2023).
tumor (continued). "The genes that showed increased expression in tumours were FN1, COL1A1 and MMP9 (p value < 0.05), which can be considered high-risk genes to indicate the prognosis level of patients with COAD." (PMID 37543674, 2023). "Immunohistochemistry results indicated that COL1A1 was highly expressed in tumor tissues, but more abundantly expressed in the stromal, whereas EPHB2 was also highly expressed in tumor tissues." (PMID 37091977, 2023). "It's pivotal for identifying fusion genes such as COL1A1-PDGFB in DFSP and NTRK in CFS, while also quantifying tumor burden and aiding post-treatment monitoring." (PMID 37920823, 2023). "COL1A2, COL1A1, COL6A3, and SDC1 were expressed at higher levels in tumor tissue compared with normal tissue in the TCGA-BC, TCGA-CRC, and TCGA-ESCA datasets." (PMID 38002057, 2023). "Tentative identification of the discriminative molecular features showed that collagen fragments (COL1A1, COL1A2, and COL3A1) play a fundamental role in tumor development." (PMID 35956764, 2022). "In summary, this present study showed that radiotherapy significantly upregulated the expression of COL1A1, COL3A1, and COL1A2 genes in BCa tumor tissues." (PMID 35274048, 2022). "The WB showed that, compared to the control group, tumor tissues with stable overexpression of MIR99AHG had decreased expression of the TGF-β1, Vimentin, and ACTA2 and COL1A1." (PMID 36138468, 2022). "We observed that culture media conditioned with A549 in the presence of TGFβ induced an increase in the expression of COL1A1 and VIM, both in CAFs and in non-tumor NFs." (PMID 35743206, 2022). "The fibroblast-deriving COL1A1 is involved in extracellular matrix (ECM) remodeling, tumor cell adhesion, and cell migration." (PMID 36038612, 2022). "We then analyzed the expression profiles of COL1A1, COL4A1, and COL6A2 in TAF and ITGA2, ITGAV, and ITGA1 in tumor cells." (PMID 35322024, 2022). "To better demonstrate the role of COL1A1-ITGA2 interaction on the transcriptomic diversity of tumor cells, we now performed co-culture experiments of ITGA2 knockdown tumor cells and COL1A1 silenced TAFs." (PMID 35322024, 2022). "TAMs and CAFs were classified according to their tumor origin and high expression of SPP1, C1QB, IL1B, S100A8, S100A9 and type I collagens (COL1A1 and COL1A2)." (PMID 36209225, 2022). "Increased production and crosslinking of collagen, such as COL1A1, increase the stiffness of ECM, leading to the promotion of tumor progression through increased integrin signaling." (PMID 35311066, 2022). "From the analysis of the most relevant m/z features for the classification, as calculated by forward feature extraction, we can conclude that COL1A1, COL1A2, and COL3A1 play a central role in tumor progression." (PMID 35956764, 2022). "The mechanistic investigation revealed that miR-29b-3p directly targeted COL1A1 and COL5A1, thereby suppressing ECM remodeling, which is crucial for tumor invasion and metastasis." (PMID 35530352, 2022). "Therefore, COL1A1 may affect tumor development through WNT/PCP signaling pathway." (PMID 35789341, 2022). "We recently demonstrated that inhibition of COL1A1 expression within the GBM tumor cells reprogramed the tumoral microenvironment and inhibited tumor invasion and progression." (PMID 36276147, 2022). "ITGA2 interacted with COL1A1, COL1A2, COL8A1, FN1, and HSPG2, mediating the tumor cell–fibroblast and tumor cell–endothelial cell connection." (PMID 35719923, 2022). "Thus, COL1A1 expression might be related to tumor immune microenvironment." (PMID 33490271, 2021). "Solid cancers synthesise high amounts of ECM proteins and COL1A1; and ECM remodelling promotes primary tumour progression and metastasis." (PMID 33980846, 2021). "The ECM components COL1A1, COL3A1, COL4A1, and fibronectin 1 (FN1), are critical regulators during tumor metastasis, so we examined their expression in the DCN and control cells using qPCR." (PMID 34504839, 2021).